GNLY (granulysin)
Diseases named in the same sentence as GNLY in open-access papers (continued):
Sharing a sentence is not in itself a finding about the gene and the disease.
cancer (52 papers, 2010 to 2026). A tumor composed of atypical neoplastic, often pleomorphic cells that invade other tissues. "GNLY is predominantly expressed in human CTLs and NK cells and has been implicated in a plethora of pathological conditions, including infections, cancer, transplantation, and dermatological disorders." (PMID 38057716, 2023). "Overall, cytokines associated with effector lymphocyte cytotoxicity response (IFNg, perforin, granzyme A, granzyme B, and granulysin), cell death (FasL and TNFa), and IL-17A showed strong positive correlation with cancer cell killing (p = 0.025 to p < 0.0001)." (PMID 40589567, 2025). "Ascore comprises four genes (CERCAM, EMP1, GNLY, and PTPRR), which have been previously reported to be strongly associated with cancer." (PMID 38341586, 2024). "Some markers CD14 (monocyte), CD3D (CD4+T cells), CD3E (CD8+T cells), CD68 (macrophage), CST3 (myeloid cells), GNLY (NK cells), KRT18 (epithelial cells), and NKG7 (NK cells) were positively associated with TMSB10 in all cancers." (PMID 37275863, 2023). "Studies have shown that NK EVs contain perforin, granzyme A, granzyme B, granulysin, and FasL, proteins that activate both intrinsic and extrinsic apoptosis pathways in cancer cells." (PMID 37818374, 2023). "Many studies have shown the involvement of GNLY in the targeting of tumors by cytotoxic immune cells and have revealed a correlation between the presence of granulysin and a more positive cancer prognosis." (PMID 38083905, 2023). "Owing to the pre-existing immunity in hot tumors, ICI can disrupt tolerance to help CD8+ T cells target cancer cells by releasing perforin, granulysin, and granzymes." (PMID 35962309, 2022). "Cytotoxic T lymphocytes can directly kill cancer cells by releasing perforin, granzymes, and granulysin, while helper T lymphocytes act by regulating adaptive immunity." (PMID 36303207, 2022). "Perforin and granulysin are needed to maintain normal immune surveillance and reduction in infection, specifically in immunocompromised cancer patients." (PMID 35564767, 2022). "Recent studies using RNA sequencing in human cancers have reported cytotoxic characteristics of CD4+ T cells, which express cytolytic molecules such as granzymes, perforin, and granulysin in the tumors and circulation of cancer patients." (PMID 36613591, 2022). "An early report established a link between lower expression of granulysin on NK cells and cancer progression in patients with disparate types of cancer." (PMID 32466293, 2020). "Increased granulysin expression has been correlated to good prognosis in a wide variety of cancers, including solid and hematological malignancies." (PMID 32466293, 2020). "The CD4-positive T cells augment the immune response against cancers, and CD8-positive cytotoxic T lymphocytes (CTL) directly kill the cancer cells through the degranulation of granzyme, granulysin, or perforin." (PMID 30662919, 2018). "GNLY is important in a variety of human diseases, including infections, transplantation, and cancer." (PMID 29137359, 2017). "Collectively, our findings strongly supported that HIS mouse as a valuable model for studying human cancer under an intact immune system and the role of GNLY in tumorigenesis." (PMID 29137359, 2017). "HIS serves as a powerful preclinical model for examining human infections, cancer, transplantation and immune-mediated diseases as well as with the functional roles of GNLY in these processes." (PMID 29137359, 2017). "Among those significantly increased with BRAF+/−MEKi were 14 of 17 genes of a Th1 signature associated with immunologic rejection of cancer, with GNLY, IFNG, and GBP1 the only genes not represented." (PMID 41514118, 2026). "Moreover, in the presence of GNLY blocking mAb, stronger inhibition of apoptosis occurred in mNK-sEV treated cancer cells than in conNK-sEV treated cancer cells." (PMID 39075563, 2024).
cancer (continued). "CD4 Teff could induce humeral immune response and enhance cellular immune response by secreting pro-inflammatory cytokines, and CD8 Teff could directly eliminate cancer cells by secreting granzymes, perforin and granulysin." (PMID 38348038, 2024). "Cancer cells were first treated with blocking mAbs against GNLY prior to sEV treatment." (PMID 39075563, 2024). "Since mNK-sEV exerted their cytotoxicity by activating apoptotic pathway in cancer cells, we next examined whether GNLY plays an indispensable role in the activated apoptotic pathway by mNK-sEV treatment." (PMID 39075563, 2024). "The serum concentrations of granulysin determine the immune response in patients with cancer." (PMID 37534217, 2023). "Studies in humans and NHP have shown that IPP- or HMBPP-activated Vγ2Vδ2 T cells can readily produce Th1 cytokines IFN-γ/TNF-α and cytotoxic granule molecules perforin (PRF), granzyme A/B (GZMA/B), and granulysin (GNLY), and consistently exhibit antimicrobial and anti-cancer activities." (PMID 31080452, 2019). "GNLY expression level was correlated with the prognosis and progression of cancer patients." (PMID 29137359, 2017). "Consequently, GNLY blockade resulted in the reduction of apoptosis in cancer cells." (PMID 39075563, 2024). "In the context of cancer, granulysin-mediated apoptosis may be caspase-dependent or independent." (PMID 32466293, 2020). "However, the level of granulysin increased substantially in cancer cells." (PMID 24828484, 2014). "Indeed, reduced expression of granulysin in patients is correlated with the progression of cancer." (PMID 24828484, 2014). "Some studies demonstrated a correlation between GNLY and GZMB expressions and clinical outcomes in patients with several cancers." (PMID 35265561, 2022). "The hypergeometric distribution showed that in the cancer region, TM4SF1 + cancer cells (Epi-C0) colocalized with the two subtypes of NK cells (T/NK-C4: GNLY and T/NK-C5: NKG7) and mast cells (Mye-C0: TPSB2, Mye-C9: CPA3)." (PMID 36434043, 2022). "CD8 + T cells can kill cancer cells by releasing PRF1, GNLY, or GZM and break tolerance as a preexisting immune response, enhancing immunotherapy via the PD-1/PD-L1 immune inhibitory axis." (PMID 34790235, 2021). "Lung tumor biopsies obtained from HIS mice showed increased cleaved caspase 3, 7 and PARA expression, indicating the apoptotic function of GNLY in both CL1-5 and HT29 cancer cells." (PMID 29137359, 2017). "Interestingly, CD4+ Texterm phenotype exhibited the highest expression of cytotoxic markers (PRF1, GZMA, GZMB, IFNG, and GNLY), aligning with recent discoveries indicating that cytotoxic CD4+ T cells within tumors can directly kill cancer cells." (PMID 40335494, 2025). "The cytolytic molecules, such as granzymeA, granzyme B, perforin, and granulysin from γδ-T exosomes,induced specific apoptosis of cancer cells without harming normalcells." (PMID 39862206, 2025). "Against all tested cancer cell lines, the BAFF CAR-T cells released significantly higher levels of the pro-inflammatory cytokines TNF-α and IFN-γ, lytic enzymes granzymes A and B and perforin, soluble Fas ligand (sFasL), and granulysin." (PMID 35017485, 2022). "In addition to transcription factors, in AML samples, we identified the upregulation of genes that were reported to accelerate leukaemogenesis, including S100A8, S100A9, and RPS26, and the downregulation of genes related to cancer control and defence, such as XIST, GIMAP7, NKG7, and GNLY." (PMID 37615858, 2024). "Interestingly, the expression levels of the cytotoxic effectors PRF1, GNLY, GZMA, GZMB and GZMH in CD8+ Tex subclusters were even richer than those in CD8+ Teff subclusters, which implied that CD8+ Tex cells still tended to respond to cancer cells." (PMID 35562760, 2022). "No direct impairment of granulysin function has been described in cancer so far." (PMID 32466293, 2020).
infection (31 papers, 2007 to 2025). The state of being infected such as from the introduction of a foreign agent such as serum, vaccine, antigenic substance or organism. "In the macaque model of TB, CD8+ T cells expressing PRF1, GZMB, and GNLY were associated with protective granuloma and linked with protection from Mtb in the early stage of infection." (PMID 39836471, 2025). "In the same way, at 7 days before infection, expression of GNLY, encoding a protein with robust antimicrobial activity against various pathogens, including Salmonella, was slightly less expressed in HS pigs." (PMID 36629432, 2023). "Our experiments demonstrate a profound remodelling of the iRBC plasma membrane with an efficient depletion of cholesterol and a massive externalisation of PS in the course of the infection that defines the susceptibiltiy of GNLY and PFN lysis." (PMID 34093532, 2021). "However, chronic TB is linked to decreased production of perforin and granulysin in CD8+ T cells at the infection site, potentially contributing to disease progression." (PMID 40825006, 2025). "Myeloid cytotoxic pathways (such as granzyme, perforin, and granulysin) were among the downregulated infection-response genes." (PMID 38755198, 2024). "The number of differentiated granulysin (GNLY)+CD8+ CTLs increases during infection and convalescence, yet the exhaustion of CD8+ CTLs in COVID-19 disease was associated with the increased expression of the inhibitory receptor NKG2A." (PMID 38162653, 2023). "Expression of GNLY was slightly lower in HS than in LS; 20 days before inoculation and 1 day after infection, its expression in HS pigs was downregulated compared to controls." (PMID 36629432, 2023). "The expression levels of GNLY, another important antimicrobial peptide, showed ~ 1.2-fold up-regulation at 6 h and ~ 2.5-fold up-regulation at 24 h post-infection." (PMID 32275661, 2020). "Higher production of IL-17A, IFN-γ, IL-10, IP-10, GM-CSF, sFasL, Granzyme A, Granzyme B, Granulysin, and Perforin following infection positively correlated with HIV replication." (PMID 33214610, 2020). "In Mtb infections, the combined action of perforin and the antibacterial agent granulysin, both of which are expressed in the granules of CTLs and NK cells, influences the outcome of infection." (PMID 25209422, 2014). "We identified three previously reported biomarkers of infection (neutrophil gelatinase-associated lipocalin (NGAL), granulysin and resistin) and measured gene expression using quantitative real-time PCR." (PMID 22559298, 2012). "This is supported by the finding of reduced perforin and granulysin coexpression in CD8+ T-cells found at the site of infection in chronic TB." (PMID 21234358, 2011). "Host defense mechanisms against intracellular microbes require induction of effector molecules such as granulysin during infection." (PMID 17596262, 2007). "Furthermore, we observed that the expression levels of granzyme A, granzyme B, perforin and granulysin in the indirect contact group were downregulated to varying degrees at 48 h post-infection." (PMID 40370406, 2025). "Additionally, we showed that NK cells expressing granulysin in mice protect the developing fetuses from the effects of a maternal infection with the bacterium." (PMID 38215172, 2024). "These LAM-responsive unconventional CD8+ T-cells co-express perforin, granzyme B, and granulysin and may have a key role in infection control." (PMID 36160177, 2022). "PRF1, GZMB, and GNLY genes expressed at the fifth day of infection were upregulated." (PMID 34945761, 2021). "Granulysin (GNLY), an antimicrobial peptide contained in cytotoxic granules in human natural killer cells and cytolytic T lymphocytes but not in mouse cells, has been shown to mediate T. gondii death in vitro and GNLY-transgenic mice are protected against infection by T." (PMID 33324583, 2020).
infection (continued). "Finally, we found that the transgenic mice that express human GNLY, an anti-microbial peptide produced by CTLs, are more resistant to infection with P. yoelii blood-stage." (PMID 32913355, 2020). "Comparisons across the early- and late-stages of infection showed that cells from CHs had an early expression of genes associated with exhaustion (PDCD1, ENTPD1), and cytotoxicity, including NK-like genes NKG7, GNLY, KLRC2, and KLRC3 (encoding for NKG2C and NKG2E, respectively)." (PMID 36477661, 2022). "Thus, future investigations are required to explore the roles of GNLY and other antimicrobial molecules as biomarkers, for example, in prospective cohort studies with follow up of blood levels during the first two years after infection." (PMID 27756230, 2016). "In contrast, reduced fetus weights were observed when WT mice that do not express GNLY were used, suggesting that GNLY reduces the infection’s effect on the fetuses." (PMID 38215172, 2024). "On the other hand, early after infection, compared to noninfected pigs, expression of GNLY and CSF3 but also that of TLR1, 3, and 6, key players of innate response development, was downregulated only in HS pigs." (PMID 36629432, 2023). "Our findings contrast with those in model systems like mice, which notably do not have the capacity to sterilize sites of infection and whose CD8 T cells also do not express granulysin." (PMID 35483355, 2022).
bacterial infections (5 papers, 2013 to 2024). "Studies on uNKs in local bacterial infections in pregnancy are scarce;83–85 one study on decidual NKs (dNKs) showed that human dNKs selectively transfer granulysin to kill intracellular Listeria monocytogenes in placental cells." (PMID 38310089, 2024). "The cytolytic granules have been shown to contain chemokines such as CCL3, CCL4 and CCL5 in addition to the classical mediators of cytotoxicity (GZMB, PRF1 and GNLY), in both viral and bacterial infections, indicating their role in cytolysis." (PMID 38501302, 2024). "An upregulation of granulysin is part of the adaptive immune response against bacterial infections." (PMID 28003017, 2016).
benign tumors (1 paper, 2023). "Previous studies have suggested that serum granulysin levels are biomarkers in patients with benign tumors and malignant diseases." (PMID 37534217, 2023).
hematological malignancies (1 paper, 2021). "Although many studies have evaluated serum GNLY as a biomarker in cases with solid or hematological malignancies, few studies have reported serum GNLY concentrations in RA cases." (PMID 34691030, 2021).
GNLY also shares sentences with these, for which no sentence is quoted: Stevens-Johnson syndrome (3 papers); immune diseases (2); rheumatoid arthritis (2); triple-negative breast carcinoma (2); abortion (1); allergic rhinitis (1); Angina (1); brucellosis (1); bullous skin diseases (1); celiac disease (1); chronic obstructive pulmonary disease (1); colitis (1); colon adenocarcinoma (1); cutaneous lupus erythematosus (1); depression (1); diabetes mellitus (1); diffuse large B-cell lymphoma (1); ductal carcinoma in situ (1); Encephalopathy (1); Graves disease (1); hair diseases (1); hepatitis B (1); Hodgkins lymphoma (1); hypersensitive pneumonitis (1); Infertility (1); leukoplakia (1); lichen planus (1); lung adenocarcinoma (1); multiple myeloma (1); Mycobacterium infection (1).
A further 14 diseases each share a sentence with GNLY in 1 paper.